ATF4 (activating transcription factor 4)
Diseases named in the same sentence as ATF4 in open-access papers (continued):
Sharing a sentence is not in itself a finding about the gene and the disease.
gastric cancer (continued). "In conclusion, our results suggest that ISR activation by salubrinal up-regulates ATF4-modulated gene expression, increases GSH synthesis, and decreases cisplatin-induced oxidative damage, which contribute to cisplatin resistance in gastric cancer cells." (PMID 30380689, 2018). "In the present study, we used the eIF2α phosphatase inhibitor salubrinal to persistently activate the eIF2α–ATF4 pathway and evaluated the role of ISR in the cisplatin resistance of human gastric cancer cells." (PMID 30380689, 2018). "The identification of ATF4-mediated SIRT1 expression level increases in gastric cancer cells, prompted us to analyze the role of this pathway in gastric cancer MDR." (PMID 22363646, 2012). "However, the expression and function of ATF4 in gastric cancer MDR remains unknown." (PMID 22363646, 2012). "Additionally, knockdown of ATF4 expression greatly impaired BTZ augmented DDP‐induced PARP1 cleavage, indicating that BTZ enhanced the toxicity of DDP in gastric cancer cells depending on ATF4‐activating apoptosis." (PMID 34709767, 2021). "Furthermore, ER stress inducer tunicamycin augmented HMGCS1 expression in gastric cancer cells, and HMGCS1 overexpression raised levels of p-eIF2α, p-PERK, ATF4, and ER stress markers." (PMID 32349352, 2020). "Moreover, higher expression levels of ATF4 and its downstream genes TRB3, HO-1, PCK2, and xCT in gastric cancers were significantly correlated with poorer prognosis for patients receiving chemotherapy." (PMID 30380689, 2018). "Thus, we next examined the expressions of ER stress-related proteins, such as p-PERK, p-eIF2α, ATF4, and CHOP in AF-treated gastric cancer cells." (PMID 26431378, 2015). "Overexpressed TLK2 binds to ATF4 to enhance asparagine synthetase (ASNA) transcription level and prevent ubiquitination of ASNA, thus promoting the progression of gastric cancer (GC) by reprogramming amino acid metabolism." (PMID 38343446, 2023). "Stabilisation of the ATF4 protein with bortezomib (BTZ), an anticancer drug that inhibits proteasomal degradation, might be a rational strategy to improve chemotherapeutic efficacy in gastric cancer." (PMID 34709767, 2021). "Stabilisation of ATF4 protein with proteasomal degradation inhibitor BTZ, which has been applied clinically for the treatment of multiple myeloma and other cancers, might be a rational strategy to improve chemotherapeutic efficacy in gastric cancer." (PMID 34709767, 2021). "However, transient incubation with low dose (0.1–0.4 μg/ml) cisplatin increased ATF4 expression (data not shown), while transient incubation with a relatively high dose (>0.8 μg/ml), gradually reduced ATF4 expression in gastric cancer cells." (PMID 34709767, 2021). "To evaluate whether the activation of ISR is able to induce cisplatin resistance, we treated three human gastric cancer cell lines (AGS, AZ521, NUGC-3) with the eIF2α phosphatase inhibitor salubrinal to maintain the phosphorylation status of eIF2α and to increase ATF4 protein expression levels." (PMID 30380689, 2018). "In this study, we demonstrated that mitochondrial dysfunction induced by oligomycin and antimycin A might enhance cisplatin resistance in human gastric cancer cells through increased xCT expression and intracellular GSH levels, as well as through the ROS activation of the GCN2-eIF2α-ATF4 pathway." (PMID 27708226, 2016). "We showed that ATF4 had a key role in the regulation of MDR in gastric cancer cells in response to chemotherapy and these findings suggest that targeting ATF4 could relieve therapeutic resistance in gastric cancer." (PMID 22363646, 2012). "Compared to the surrounding non-cancerous tissues, the expression of ATF4 and SHH in stomach cancer tissues was greater, and the correlation between ATF4 and SHH was detected in 80 clinical gastric cancer tissues by immunohistochemistry score." (PMID 36900220, 2023).
gastric cancer (continued). "ATF4 is not identified to regulate SHH, inhibiting the Sonic Hedgehog signaling pathway and preventing the onset and spread of gastric cancer." (PMID 36900220, 2023). "Next, we examined SIRT1, ATF4, MDR1, MRP, Bcl-2, and Bax expression levels after 24 hours' incubation with or without the indicated doses of EX-527 in the gastric cancer cells used above." (PMID 22363646, 2012).
colon carcinoma (26 papers, 2017 to 2026). "Taken together, our studies identified ER stress as a novel mechanism that triggers PHLPP downregulation; and PHLPP-loss promotes chemoresistance by upregulating the eIF2α/ATF4 signaling axis in colon cancer cells." (PMID 34663797, 2021). "Here, we report that activating transcription factor 4 (ATF4)-dependent REDD1/DDIT4 expression is required for survival of colon tumor cells undergoing endoplasmic reticulum (ER) stress through the modulation of TRAILR2/DR5 gene expression." (PMID 41904147, 2026). "Collectively, our findings suggest that glutamine deprivation, through cFLIPL downregulation, facilitates TRAIL-R2/DR5-mediated NF-κB activation, which, in concert with the GCN2/ATF4 signaling pathway, drives IL-8 gene expression in human colon cancer cells." (PMID 40683891, 2025). "Our findings indicate that glutamine deprivation induces IL-8 gene expression and secretion in glutamine-addicted colon cancer cells via the GCN2/ATF4 pathway." (PMID 40683891, 2025). "Matrine shows antiproliferation and promotes the ferroptosis of colon cancer cells by upregulating the ferroptosis-inducing ATF4 gene and downregulating the ferroptosis-inhibiting genes (GPX4 and SLC7A11)." (PMID 38892270, 2024). "Mechanistically, gallic acid regulates the ferroptosis of colon cancer cells by upregulating the ferroptosis-inducing ATF4 gene and downregulating ferroptosis-inhibiting genes (GPX4 and SLC7A11)." (PMID 38892270, 2024). "EGCG triggers the ER stress of colon cancer cells by upregulating the ferroptosis-inducing ATF4 gene." (PMID 38892270, 2024). "To address this, we compared the effects of Tg on cell cycle distribution using HCT116 colon cancer cells and an ATF4-def subline that we generated recently." (PMID 38130926, 2023). "For example, Zerumbone and Parthenolide activated eIF2α through ER stress, thus inducing the transcription of ATF4 in human colon cancer cells and lung cells." (PMID 34195076, 2021). "Our work suggests an interesting possibility that deregulated proteostasis with overstressed protein quality control is a druggable vulnerability of colon cancers driven by Wnt/Myc and mutant RAS/RAF, which predisposes to hyperactivation of ATF4/CHOP and catastrophic ER stress." (PMID 28030835, 2017). "Knocking down NOX5 attenuated the inhibition of proliferation and colony forming ability induced by PD in colon cancer cells and reversed the expression of C/EBP-homologous protein (CHOP) and activating transcription factor 4 (ATF4) proteins." (PMID 39850563, 2024). "As expected, pretreatment with NAC significantly reduced inhibitory effects of PD and notably reversed the protein expressions of ATF4 and CHOP in colon cancer cells." (PMID 39850563, 2024). "As shown in the results, increased expression of GRP78, ATF4, and CHOP was detected in colon cancer cells after combination therapy." (PMID 37833257, 2023). "Following our results, a transcriptomic analysis of colon cancer cells showed that rosemary polyphenols induced the activation of IRE1/XBP1 and PERK/ATF4 as a protective sensitization mechanism." (PMID 34836245, 2021). "Our results demonstrate that NAC was able to reduce cell death and the expression of ER stress–related markers (phospho-IRE1α, phospho-JNK, ATF4, and CHOP) activated by NB extract in colon cancer HCT-116 cells." (PMID 34456713, 2021). "As verified by RT-qPCR, a dysfunction of mitochondrial respiration chain and ER stress resulted in a partially ATF4-dependent stimulation of KRT16, FAM129A and HKDC1 expression in the HCT116 colon carcinoma cell line." (PMID 29420561, 2018).
colon carcinoma (continued). "Furthermore, silencing NOX5 reversed the elevation of ATF4 and CHOP following PD treatment, suggesting that NOX5 is a key mediator in the PD-induced ROS-mediated ER stress pathway in colon cancer cells." (PMID 39850563, 2024). "All these results suggested that PD may induce cell death by elevating ROS production and activating ATF4 and CHOP signaling pathway in colon cancer cells." (PMID 39850563, 2024). "Indeed, cystine inhibited GCN2 phosphorylation and downregulated nuclear ATF4 protein levels, which decreased transcription of SESN2 and ultimately activated mTORC1 in both HCT116 and RKO colon cancer cell lines." (PMID 34045438, 2021). "Similarly, pretreatment of colon cancer cell with an ER stress inhibitor, 4-phenylbutyric acid (4-PBA), markedly attenuated PD induced cell death and the expressions of ATF4 and CHOP, suggesting that ROS-mediated ER stress plays a key role in the PD-mediated cell death." (PMID 39850563, 2024).
multiple myeloma (24 papers, 2013 to 2025). "In multiple myeloma cells, sensitivity to bortezomib treatment was associated with higher expression of ATF4 and loss of its expression lead to lower levels of Noxa, CHOP and DR5." (PMID 34630117, 2021). "Treatment with bortezomib activates PERK and eIF2α phosphorylation in multiple myeloma cells, followed by the induction of ATF4 and CHOP." (PMID 40459063, 2025). "Downregulation of HDAC4 increases ATF4 expression under ERS, which is associated with increased pro-apoptotic CHOP expression and enhanced apoptosis of multiple myeloma cells." (PMID 38879481, 2024). "Downregulation of HDAC4 increases ATF4 expression under ERS conditions and is associated with increased pro-apoptotic CHOP expression and enhanced apoptosis in multiple myeloma cells." (PMID 38879481, 2024). "A separate study in multiple myeloma suggested the use of ATF4 as a predictive therapy response biomarker for bortezomib and dexamethasone combination treatment." (PMID 34630117, 2021). "Ribosome occupancy of this single methionine is of unclear significance, though it may also play an uncharacterized role in regulating ATF4 translation in myeloma." (PMID 24171104, 2013). "In lymphoma and myeloma, inhibiting SRPK1 induces ER stress and death through ATF4/CHOP activation and AKT suppression." (PMID 41551143, 2025). "As expected, compared with the DMSO group, CD27 expression was increased in myeloma cells, PERK and ATF4 mRNA and protein expression were correspondingly increased." (PMID 38504180, 2024). "In multiple myeloma (MM), HDAC4 protected cells from ER-stress-mediated apoptosis by repressing activating transcription factor 4 (ATF4)." (PMID 36982651, 2023). "Studies have revealed the importance of the ATF4/CHOP pathway in the LW-213-induced apoptosis of cutaneous T-cell lymphoma cells and the aspirin-induced apoptosis in multiple myeloma cells." (PMID 36303126, 2022). "As myeloma plasma cells produce a large amount of Igs, integrated stress response mechanisms and UPR are constantly activated and, thus, ATF4 and CHOP expression levels are higher than in normal plasma cells." (PMID 33028016, 2020). "In multiple myeloma cell lines, the selective class IIa HDAC inhibitor TMP269 enhances cytotoxicity, up-regulates ATF4 and CHOP, and induces apoptosis; however, the enhanced cytotoxicity is abrogated by ATF4 knockdown." (PMID 28134767, 2017). "However, upon transformation, myeloma cells require the further support of PERK, allowing transcription of the ATF4 targets that ameliorate oxidative stress." (PMID 23781234, 2013). "In two statin-sensitive AML cell lines, OCI-AML3 and MOLM13, pitavastatin did not induce ATF4 and ISRIB did not affect sensitization to venetoclax, suggesting statin-mediated activation of the ISR is multiple myeloma specific." (PMID 37956312, 2023).
leukemia (22 papers, 2015 to 2025). A malignant (clonal) hematologic disorder, involving hematopoietic stem cells and characterized by the presence of primitive or atypical myeloid or lymphoid cells in the bone marrow and the blood. "ONC201/TIC10 caused apoptosis through ATF4 in lymphoma and leukemia cells and inhibited mTORC1 signaling through the upregulation of ATF4 and DDIT4." (PMID 37772709, 2023). "Autophagy and ATF4 play a key role in FLT3-ITD mutation mediated leukemia proliferation and survival." (PMID 32312983, 2020). "Collectively, these results indicate that the acute induction of ATF4-regulated pathways can selectively induce cell death of p30-expressing cells, and suggest that this could be exploited as a vulnerability to treat leukemia patients with N-terminal CEBPA mutations." (PMID 40221437, 2025). "This identified top 10 TFs involving in hematopoietic cells proliferation and differentiation (SPIB, ATF4) and pathogenesis of leukemia (CEBPB, CTCF)." (PMID 38693103, 2024). "We found that BM endothelial increased p-eIF2α and ATF4 induced by leukemia was attenuated in the ECs of PERK-depleted mice." (PMID 35401837, 2022). "Our analyses reveal the network of enhancers that controls intrinsic expression of ABCB1 in human leukemia cells; the gene is a direct target of the transcription factor ATF4, which is activated through a chemotherapy-induced cellular stress response." (PMID 31770110, 2020). "All together these data demonstrate that expression of the daunorubicin drug export pump ABCB1 is dynamically regulated in leukemia cells though the ATF4-bound E3 enhancer." (PMID 31770110, 2020). "Stimulation of the EIF2/ATF4 axis appears as the very likely trigger of the increased need of serine in Gln-deprived leukemia cells." (PMID 26625201, 2016). "To verify the influence of ATF4 activity on the invasive potential of leukemia cells, we performed the matrigel transwell assay." (PMID 27802179, 2016). "The eIF2α-P/ATF4 axis is likely to play a central role in the potentiation of invasive properties of leukemia cells, as well as influence their cross-talk with bone marrow stromal fibroblasts." (PMID 27802179, 2016). "We postulate that ATF4 production in leukemia cells plays a significant role in the regulation of extracellular matrix dynamics and invasiveness of both CML and stromal cells." (PMID 27802179, 2016). "We further show that enhanced phosphorylation of eIF2α supports the invasiveness of leukemia cells in a manner dependent on the ATF4 transcription factor." (PMID 27802179, 2016). "Recently, hibiscus acid was reported as a nutraceutical approach for the treatment of chronic myelogenous leukemia due to protein response observed by activation of eIF2α/ATF4 pathway that induced cell cycle arrest at G2/M phase and DNA fragmentation in leukemia K562 cells." (PMID 36838811, 2023). "Inhibition of autophagy or ATF4 enhances the anti-leukemia effect of FLT3 inhibitors." (PMID 35794565, 2022). "Taking away the ATF4-mediated blockade, sorafenib allowed IRF7 activation and caused IL-15 transcription in the leukemia cells which caused an increase of CD8+ CD107a+ IFNγ+ T cells, which was connected to the increased elimination of leukemia cells by activated donor T cells." (PMID 35460465, 2022). "Overall, our results point to eIF2α and ATF4 as potential therapeutic targets in leukemia." (PMID 27802179, 2016). "Therefore, the expression of TXNDC12, regulated by ATF4, may function as a negative regulator of lipid peroxidation and subsequent ferroptosis in leukemia cells." (PMID 38047088, 2023). "In MDS1 and EVI1 complex locus (EVI1)-overexpressing leukemia, PRMT5 inhibition decreased the levels of the spliced cytoplasmic form of activating transcription factor 4 (ATF4) protein, resulting in increased oxidative stress, growth arrest and senescence." (PMID 40603833, 2025).
leukemia (continued). "Meanwhile, sorafenib synergizes with T cells by downregulating ATF4 expression, leading to the activation of the IRF7–IL-15 axis in leukemia cells." (PMID 41312168, 2025). "Most of the genes in the HIF1A module play leukemia-promoting roles in AML, such as HIF1A, CEBPG, JUN, and ATF4." (PMID 37691822, 2023). "In contrast, CD treatment inhibited eIF2a activation and suppressed ATF4 and JAG1 up-regulation induced by leukemia SEVs." (PMID 35401837, 2022). "Conditioned media from CML cells with constitutive activation of the eIF2α-P/ATF4 pathway induces invasiveness of bone marrow stromal fibroblasts, suggesting that eIF2α-P may be important for extracellular matrix remodeling and thus leukemia cells-stroma interactions." (PMID 27802179, 2016). "The inducible expression of TXNDC12 during ferroptosis in leukemia cells is inhibited by the knockdown of the transcription factor ATF4, rather than NFE2L2." (PMID 38047088, 2023). "Finally, we showed that small extracellular vesicles are critical mediators of endothelial PERK-eIF2a-ATF4 activation and JAG1 up-regulation in leukemia." (PMID 35401837, 2022). "Down-regulation of ATF4 partially inhibited JAG1 up-regulation and down-regulation of JAG1 recovered suppressed SCF and CXCL12 expression, attenuated VEGFα induction, and induced leukemia cell apoptosis." (PMID 35401837, 2022). "Over-expression of ATF4 led to further increased JAG1 level while down-regulation of ATF4 by siRNA decreased JAG1 level in ECs co-cultured with ICN1 leukemia cells, indicating that EC JAG1 expression is regulated by ATF4 in the leukemia microenvironment." (PMID 35401837, 2022). "Since we find DENR•MCTS1 is required for ATF4 expression in cervical cancer HeLa cells, leukemia Jurkat cells, and fibrosarcoma HT1080 cells, we postulated DENR•MCTS1 may promote ATF4 translation in many different cancers." (PMID 32938922, 2020).